CD82 (CD82 molecule)
Diseases named in the same sentence as CD82 in open-access papers (continued):
Sharing a sentence is not in itself a finding about the gene and the disease.
oesophageal cancer (1 paper, 1999). "Few cases remained KAI1/CD82-positive (9.6%; 10/104) in oesophageal cancer." (PMID 10098753, 1999). "As we could not find any reports concerning the expression of MRP-1/CD9 and KAI1/CD82 in oesophageal cancers we investigated their expression in oesophageal specimens." (PMID 10098753, 1999).
oropharyngeal squamous cell carcinoma (1 paper, 2023). "Our aim was to assess the clinical and prognostic role of liprin-α1 and CD82 in HPV-positive oropharyngeal squamous cell carcinoma (OPSCC) in comparison to HPV-negative OPSCC." (PMID 37335526, 2023).
osteoporosis (1 paper, 2023). A condition of reduced bone mass, with decreased cortical thickness and a decrease in the number and size of the trabeculae of cancellous bone (but normal chemical composition), resulting in increased fracture incidence. "However, in monocytes, the expression level of CD82 is relatively high in osteoporosis mice, and the expression level of SLC40A1 is relatively low." (PMID 37770229, 2023).
osteosarcoma (1 paper, 2023). A usually aggressive malignant bone-forming mesenchymal neoplasm, predominantly affecting adolescents and young adults. "Ten additional solid cancers such as prostate, gastric, ovarian, colon, cervical, renal clear cell carcinoma, osteosarcoma, bladder, thyroid and LSCC cancers are known to be dependent on deficiency in KAI1/CD82 expression." (PMID 37990044, 2023).
ovarian tumor (1 paper, 2023). "We compared the bulk transcriptomes of hiPSCs, COV434 and KGN ovarian tumor cells, and sorted FOXL2+CD82+ granulosa-like cells from day 5 of a polyclonal differentiation with expression of our previously identified top TFs (NR5A1, TCF21, GATA4, and RUNX1)." (PMID 36803359, 2023).
pancreatic diseases (1 paper, 2017). "We evaluated TIMP-1 and CD82 expression by immunohistochemistry in 32 cases of histological or cytological confirmed pancreatic diseases." (PMID 28030805, 2017). "In pancreatic diseases, CD82 detection helps to discriminate PDAC from other tumors (96.9% in accordance with pathology diagnosis)." (PMID 28030805, 2017).
preeclampsia (1 paper, 2024). Preeclampsia is a hypertensive disorder of pregnancy that is characterized by new-onset hypertension with proteinuria presenting after 20 weeks of gestation, and depending on mild or severe forms may initially present with severe headache, visual disturbances, and hyperreflexia. "However, the roles of NOTUM and CD82 in the context of m6A modification during preeclampsia pathogenesis remain unclear." (PMID 38765115, 2024).
pulmonary fibrosis (1 paper, 2020). Chronic progressive interstitial lung disorder characterized by the replacement of the lung tissue by connective tissue, leading to progressive dyspnea, respiratory failure, or right heart failure. "Based on these findings, we looked for CD82 protein expression in human pulmonary fibrosis (IPF), co-staining for pertinent markers of Pdgfra+ fibroblasts (PDGFR-α and COL13A1)." (PMID 32488016, 2020). "To explore the relevance of our findings in other fibrotic diseases, next we examined CD82+ stromal cells in a murine model of pulmonary fibrosis." (PMID 32488016, 2020). "We uncovered a functional role of CD82 in human myofibroblasts in localised fibrosis, but the exact molecular function of CD82+ stromal cells in pulmonary fibrosis remains unknown and represents an exciting avenue for future research." (PMID 32488016, 2020).
pulmonary TB (1 paper, 2018). "We further examined pulmonary CD82 expression between healthy controls and patients with pulmonary TB." (PMID 29760437, 2018).
retinal disease (1 paper, 2022). "Based on these previous studies showing that the anticancer effect of LEL of CD82 is involved in a potential ability to suppress motility and angiogenesis, we hypothesized that its capacity may contribute to protecting against fibrotic retinal disease." (PMID 36386228, 2022).
rhabdomyosarcoma (1 paper, 2019). A rare aggressive malignant mesenchymal neoplasm arising from skeletal muscle. "Of these genes, several may be important for rhabdomyosarcoma, including a homeobox transcription factor (PROX1), a tumor suppressor (CD82), a transposable element (PDBD5), a muscle sodium channel (SCN4A), and a long intergenic non-coding RNA (LINC00689) (see Discussion)." (PMID 31480361, 2019).
staphylococcus aureus infection (1 paper, 2025). An infectious process in which the bacteria Staphylococcus aureus is present. "On the other hands, the pathway of Staphylococcus Aureus infection highly enriched in CD82 and MIOX, the pathway of proteasome highly enriched in CDKN1A and MYCN." (PMID 39966875, 2025).
Stillbirth (1 paper, 2011). Death of the fetus in utero after at least 22 weeks of gestation. "The 211.67 kb MOCS1-LRFN2 region of BTA23 included several SNPs with significant effects on daughter stillbirth, while a BTA15 marker between two CD82 genes had the most significant effect for daughter stillbirth." (PMID 21831322, 2011).
thyroid cancer (1 paper, 2011). "Investigations performed on AUF1-depleted thyroid cancer cell lines revealed a cross-link between AUF1 and CD9, CD82, S100A4 and ENO1." (PMID 21835052, 2011). "We demonstrated that down-regulation of CD9, CD82 and RKIP may reflect an increased in vivo metastatic potential of thyroid cancer cells." (PMID 21835052, 2011).
tuberculosis (1 paper, 2018). A chronic, recurrent infection caused by the bacterium Mycobacterium tuberculosis. "The increased survival rate of CD82-deficient mice following infection with tuberculosis and the elevated levels of CD82 protein found in the inflammatory lesions of patients with tuberculosis further support a previously unrecognized role for this protein in M. tuberculosis infection." (PMID 29760437, 2018). "Notably, the levels of CD82 and RUNX1 in granulomas were elevated in tuberculosis (TB) patients, indicating that CD82 and RUNX1 have clinical significance in human TB." (PMID 29760437, 2018). "However, neither the involvement of such an epigenetic regulation of CD82 expression in tuberculosis (TB) pathogenesis nor the mechanisms by which CD82 is involved in controlling the intracellular survival of pathogenic mycobacteria in macrophages are well understood." (PMID 29760437, 2018).
urothelial carcinoma (1 paper, 2023). A malignant neoplasm derived from the transitional epithelium of the urinary tract (urinary bladder, ureter, urethra, or renal pelvis). "Using immunohistochemistry, the positivity rates for these markers were significantly different between normal bladder epithelium and urothelial carcinomas where CD82 was downregulated in carcinomas and CD133 showed upregulation in cancerous tissues." (PMID 37052868, 2023).
virus infection (1 paper, 2007). "Another example of tetraspan molecule promoting viral entry is CD82 and CD81 molecules in case of HTLV-1 virus, however in this case, binding of CD81 to viral glycoprotein E2 does not correlate with permissiveness of cells to virus infection." (PMID 17572908, 2007).
vulvar carcinoma (1 paper, 2021). "In this context, our analysis did reveal that a large majority of CD82 negative tumors (61% of 30 patients) were associated with HPV16, thus further indicating that the lack of CD82 expression may contribute to a poor prognosis in vulvar carcinomas." (PMID 34065085, 2021).
tumor (176 papers, 2003 to 2026). "A number of studies have implicated CD82 as a suppressor of metastasis and its loss has been identified in multiple tumor types." (PMID 37357305, 2023). "Because loss of RelA/p65 resulted in a significant decrease in tumour growth and the induction of the metastasis suppressor CD82, we next investigated the impact of p65 on cell migration in vitro using the wound healing assay." (PMID 34503110, 2021). "In detail, KAI1/CD82 deficiency is related to aggressive tumor behaviors, such as high drug resistance, low differentiation grade, and high recurrence rate, as well as decreased disease free and overall survival duration." (PMID 34306081, 2021). "The CD82-mediated inhibition of tumor cell movement has been linked to its binding to cholesterol, and its coalescence with lipid rafts and tetraspanin-enriched microdomains." (PMID 34503296, 2021). "Loss of RelA/p65 in human NSCLC cells grown as tumours in vivo lead to the upregulation of CD82/KAI1 and to the downregulation of ROS1 proto-oncogene mRNA levels." (PMID 34503110, 2021). "CD82 has been reported to suppress tumour metastasis and be associated with tumour cell growth and survival." (PMID 31034520, 2019). "Studies on human tumor cells reported associations between tetraspanin expression and tumor progression showing both reduced (CD82, CD9) and increased expression (CD151, Tspan8) in various cancer types." (PMID 29896201, 2018). "We found advanced tumour stage, histological grade and tumor size were significantly associated with CD82 positive expression according to our analysis results." (PMID 28881668, 2017). "Loss-expression or down-expression of CD82 can further promote the metastatic ability of tumor cells." (PMID 25889325, 2015). "The recent study of other authors suggests that the high expression of COX-2 and low expression of KAI-1/CD82 are associated with increased tumour invasiveness." (PMID 25587354, 2014). "In contrast, CD82 protein level was associated with tumor status (p = 0.033); metastatic status (p = 0) and pTNM stage (p = 0.001)." (PMID 21521534, 2011). "In our study, we demonstrated that the decreased levels of CD82 protein were strikingly associated with the tumor status and the distant metastasis." (PMID 21521534, 2011). "Other potential targets for cancer metastasis therapy could include specifically expressed downstream pathways which are regulated by the loss of KAI1/CD82 or some extracellular domains of KAI1/CD82 which may show tumor metastasis function." (PMID 34306081, 2021). "Interestingly, presence of a specific splice variant of CD82 that removes exon 7 increases tumor progression and invasion." (PMID 29946318, 2018). "Levels of KAI1/CD82 were negatively associated with tumor size, LNM, DM, and TNM stage." (PMID 30593175, 2018). "Loss-expression or down-expression of CD82 promotes tumor cell invasion and metastasis." (PMID 25889325, 2015). "In addition, these studies also demonstrated that the inactivation of the KAI1/CD82 gene was associated with tumor metastasis." (PMID 25789023, 2015). "CD82 expression was markedly increased in tumor-infiltrating immune and epithelial cells compared with normal tissues, particularly within exhausted CD8+ T cells." (PMID 41607790, 2026). "Apart from their involvement in TCR signaling, tetraspanins, such as CD81 and CD82, which are expressed in cancer cells, also influence the promotion or inhibition of tumor metastasis." (PMID 38515751, 2024). "Meanwhile, we observe upregulated CD82 expression in MM cells with favorable prognosis vs. poor prognosis (p < 0.05), which confirms that CD82 acts as a tumor suppressor." (PMID 39769169, 2024). "Deletion of the CD82/KAI1 gene results in increased tumor metastasis in various tissue types, such as the liver, colon, prostate, lungs, bladder, breasts, and more." (PMID 38534734, 2024).
tumor (continued). "KAI1/CD82 is a tumor metastasis suppressor, and the palmitoylation of KAI1/CD82 effectively blocked its motility-inhibitory activity." (PMID 38315203, 2024). "The tumor metastasis suppressor gene CD82/KAI1 has been demonstrated to impact human trophoblast invasion and migration." (PMID 38534734, 2024). "CD82/KAI1 functions as tumor suppressor that by inhibiting Wnt and TGF-β1, impairs metastasis in PCa cells and EMT mechanism." (PMID 38334836, 2024). "The direct interaction of ACKR1 on vascular endothelium with CD82/KAI1 on tumor cells leads to the inhibition of tumor cell proliferation and metastasis." (PMID 37108425, 2023). "In prostate cancer, ΔNp63, as a key regulator of CSC-related genes, cooperates with CD82 and is involved in tumor metastatic adhesion." (PMID 37182132, 2023). "Another mechanism underlying the antitumor effect of ACKR1 is related to the expression of CD82/KAI1 on tumor cells." (PMID 37108425, 2023). "CD82, one of the established human tetraspanins, is well known as a tumor metastasis suppressor gene in various types of cancers." (PMID 36386228, 2022). "For example, both CD9 and CD82 are tetraspanins that function to primarily suppress tumor growth, whereas Tspan8 and CD151 are primarily oncogenic." (PMID 35280793, 2022). "In many other cancer cell types, CD82 is a well-established tumor metastasis suppressor that represses the functions of motility-related proteins to restrain cell migration and invasion." (PMID 36386228, 2022). "Although it has been established that the palmitoylation of CD82 can regulate the biological characteristics of tumor cells, its specific molecular mechanism remains to be studied." (PMID 35538033, 2022). "CD9 (Tspan4) and CD81 (Tspan28), depending on tumor type, can promote or suppress disease progression, while some other Tspan proteins, such as CD82 (Tspan27) and CD63 (Tspan30), have solely been established as tumor suppressors." (PMID 36143328, 2022). "The primary research area of CD82 is tumors, and CD82 has been recognized as a tumor metastasis suppressor gene." (PMID 35795669, 2022). "Another suggested mechanism involving CD82 suppression of tumor metastasis is the interaction of CD82 and integrin." (PMID 34540692, 2021). "KAI1/CD82 mRNA was also identified as a direct target mRNA of miR-338-5p, which is correlated with tumor stage, metastasis, and survival rate." (PMID 34306081, 2021). "Subsequent studies demonstrated that the expression of CD82 protein is frequently lost or downregulated during tumor progression in various epithelial cancers." (PMID 34445169, 2021). "CD82 was first discovered in 1995 as a tumor metastasis suppressor in rats for the treatment of prostate cancer." (PMID 33891491, 2021). "This review will mainly focus on the understanding of the behavior of KAI1/CD82 in different types of cancers and discuss the mechanism and pathways through which it plays a role in tumor metastasis." (PMID 34306081, 2021). "To mechanistically investigate the role of TSPANs in VSCC, we selected the tetraspanins CD63 and CD82 to study, as they are well characterized as having opposite roles in tumor development and prognosis in the literature." (PMID 34065085, 2021). "Related to the Wnt Pathway, CD82 belongs to the tetraspanin family of proteins and is a tumor metastasis suppressor that has been found to be inversely correlated with cell invasion, motility, metastasis, and cell survival." (PMID 33891491, 2021). "The polymorphism site rs2303861 was identified in the CD82 (KAI1) gene, responsible for the downregulation of tumor progression of human cancers, immunity, inflammation, and cognitive function." (PMID 33923295, 2021).
tumor (continued). "A decrease in CD82 level was found to induce aggressive tumor progression, while an increased level suppressed the tumor spread (secondary tumor)." (PMID 34121877, 2021). "In fact, this scenario highly resembles the well-established established tumor-suppressive role of tetraspanins CD82, CD9, and TSPAN8 in epithelial-origin cancers, whereby they regulate E-cadherin/β-catenin complex-dependent cell-cell adhesion." (PMID 33919420, 2021). "At the tissue level, CD9 was found to be predominantly localized at the cell membrane, whereas CD63, CD81, and CD82 were primarily found in the cytoplasm of the tumor samples." (PMID 34065085, 2021). "Transcripts of well-established tumor suppressor genes (Klf6, CD82) and positive regulators of apoptosis (Pmaip1) were found to be suppressed in Eμ-TCL1;CXCR4C1013G." (PMID 34363012, 2021). "Lastly, KAI1/CD82 overexpression in the H1299 cells suppresses the tumor invasiveness and metastatic potential of NSCLC cells by inducing MMP9 inactivation via the upregulation of TIMP1." (PMID 34306081, 2021). "Current research investigating the tetraspanin CD82 mainly focuses on tumor metastasis regulation and immune recognition." (PMID 34897284, 2021). "One recently discovered function of KAI1/CD82 is to decrease tumor aggressiveness by suppressing U2AF2-mediated CD44 alternative splicing." (PMID 34306081, 2021). "The tumour suppressive actions of CD82 are due to several different mechanisms, including interference with integrin-mediated signalling through direct interactions with integrin subunits, but also by indirectly affecting other signalling pathways." (PMID 34503110, 2021). "For example, tetraspanin CD82 is frequently down‐regulated in advanced stages of cancer, and overexpression of CD82 inhibits tumour migration and invasion via regulation of several signal pathways such as hepatocyte growth factor receptor (HGFR) pathway." (PMID 33277798, 2021). "CD82 represents a canonical membrane tetraspanin, most studied in the context T-cell activation and tumour suppression." (PMID 32488016, 2020). "We subcutaneously injected control, CD82 and N157Q mutant cells using a xenograft cancer model for 6 mice per group (N=6) in nude mice 28, 29 and analyzed the tumor growth." (PMID 32483464, 2020). "CD82 as tumor metastasis suppressor plays an important role in preventing primary tumor progression to a metastatic stage." (PMID 33298014, 2020). "CD82 was found to inhibit tumor metastasis as well as cell death, senescence, angiogenesis, and so on." (PMID 33204367, 2020). "Mice injected with CD82 cells exhibited significantly reduced the tumor cell dissemination as compared with control or N157Q cells by the total tumor weight per mouse." (PMID 32483464, 2020). "In qPCR array analyses, besides promoting the expression of CDH1, KH-3 treatment also induces the expression of CD82, a tumor metastasis suppressor." (PMID 32332873, 2020). "CD82, a tumour suppressor, was significantly overexpressed in the PC3KD cells, but significantly decreased in LNCaPKD cells." (PMID 29674723, 2018). "Multivariate analysis demonstrated that VM+, Notch4+, DLL4+, and/or KAI1/CD82+ specimens, and tumor size, LNM, distant metastasis (DM), and TNM stage, were independent prognostic factors for NSCLC." (PMID 30593175, 2018). "Overall, studies on the association between tumor metastasis and prognosis suggest that VM, Notch4, DLL4, and KAI1/CD82 affect cancer progression." (PMID 30593175, 2018). "Its expression on endothelial cells also inhibited metastasis through interaction with CD82/KAI on tumor cells to induce their senescence." (PMID 29879116, 2018). "Overall, our findings indicate that complex interrelationships between the VM, Notch4, DLL4, and KAI1/CD82 in tumor progression." (PMID 30593175, 2018). "The positive expression rate of KAI1/CD82 was inversely correlated with tumor size, LNM, TNM stage, and DM." (PMID 30593175, 2018).